CRP (C-reactive protein)
Diseases named in the same sentence as CRP in open-access papers (continued):
Sharing a sentence is not in itself a finding about the gene and the disease.
COVID-19 (continued). "Based on the molecular mechanism explained above, CRP causes tissue damage by binding to ischemic cells and is hence causally participating in the magnification of irreversible lung tissue damage in COVID-19." (PMID 37626775, 2023). "This was further supported by other studies that indicated male gender, elevated CRP levels, and high neutrophil-to-lymphocyte ratio to be risk factors for COVID-19-associated liver injury." (PMID 36902854, 2023). "Our study indicated that elevated CRP levels upon admission were related to an increased risk of mortality among COVID-19 participants." (PMID 37362565, 2023). "Both periodontitis and COVID-19 increase systemic inflammation levels and associated markers, such as IL-6 and CRP." (PMID 37568161, 2023). "Compared with the linear regression relationship, the curve relationship in this study can more scientifically and accurately reflect the judgment value of CRP level on the mortality risk of patients with COVID-19." (PMID 37990060, 2023). "liver injury also associated with severe and critical COVID-19, increased C-reactive protein, elevated erythrocyte sedimentation rate, mechanical ventilation, ICU admission, and Qing-Fei-Pai-Du-Tang treatment." (PMID 36860673, 2023). "Patients with COVID-19 are more likely to have thrombotic dysfunction, and those with severe symptoms had increased C-reactive protein levels and higher thrombotic risk." (PMID 36798637, 2023). "Similar to overall and digestive cancer mortalities, increase in CRP was associated with increased mortality risk to COVID-19 in Blacks (HR = 1.043 [1.004,1.082], p = 0.030)." (PMID 36963080, 2023). "Systemic inflammatory markers such as C-reactive protein (CRP) have higher values in patients with COVID-19-associated pulmonary artery thrombosis compared with those without pulmonary thrombi." (PMID 36979908, 2023). "Persistently elevated inflammatory markers (IL-6 and CRP) were risk factors for unfavorable outcomes, while low serum anti-S1/S2 IgG and ambulatory acute COVID-19 correlated with better recovery." (PMID 37893068, 2023). "In our cohort of severe COVID-19 patients, the prognostic value of CT scores seems, therefore, greater than basic clinical risk factors such as age, gender, CRP, or PaO2/FiO2 and comparable to laboratory biomarkers, such as IL-6 and IL-8." (PMID 37218940, 2023). "A poorer clinical outcome in unvaccinated residents with COVID-19 in our study was associated with higher leukocyte counts and increased NLRs, as well as with increased CRP and LDH levels." (PMID 36818555, 2023). "Multiple linear regression was used to explore the association between DII and E-DII and CRP, blood cell counts, and hospitalization in patients with COVID-19." (PMID 37063325, 2023). "COVID-19 can initiate inflammation and cause manic symptoms in the acute stage of a disease by producing the interleukins IL-6, IL-10, and plasma C-reactive protein (CRP)." (PMID 37723515, 2023). "Systemic inflammatory markers, such as IL-6 and CRP, were associated with disease severity and mortality among COVID-19 patients." (PMID 36744129, 2023). "Negative wellbeing is also associated with stress-induced elevations of inflammation, such as C-reactive protein, interleukin-6, fibrinogen, and white blood cell, which are biomarkers of critical COVID-19 and associated with mortality." (PMID 37213603, 2023). "Since early in the SARS-CoV-2 pandemic, high serum CRP concentrations, a good predictor of adverse outcome, have been associated with the severity and complications of COVID-19 patients." (PMID 37667198, 2023). "In a multicenter prospective cross-sectional study with 115 COVID-19 patients, severity was negatively associated in the multivariate analysis with Shannon diversity index (OR = 2.85) and C-reactive protein level higher than 96.8 mg/L (OR = 3.45)." (PMID 37596518, 2023). "Three known risk factors for COVID-19 severity were assessed in conjunction with CRP in our analysis: patient sex, age, and BMI." (PMID 38003780, 2023).
COVID-19 (continued). "A regression model was built using NLR, LDH, anisocytosis coefficient, CRP, and other associated respiratory diseases as clinical elements affecting SaO2 in COVID-19 patients, as well as age and sex as covariates." (PMID 36829793, 2023). "Another group, reported lactic dehydrogenase (LDH), lymphocyte, and high-sensitivity C-reactive protein (hs-CRP) were associated with the survival of COVID-19 patients." (PMID 38014372, 2023). "Elevated CRP levels have been linked to increased risk of organ failure and mortality in COVID-19 patients." (PMID 38585537, 2023). "In this prospective observational study, we demonstrated that IL-6, PCT, and CRP were equally able to identify patients at low risk for severe COVID-19 progression already at hospital admission." (PMID 37937220, 2023). "The PCT and CRP values associated with infections were lower than those observed in non-COVID-19 patients." (PMID 37887237, 2023). "COVID-19 severity was associated with age, glucose in the blood, CRP, LDH, scoring index of chest x-ray, quantity and percentage of neutrophils, WBC count, fibrinogen, specific gravity, and protein in the pleural fluid." (PMID 36668902, 2023). "COVID-19 associated KLD patients revealed higher levels of CRP, ferritin, procalcitonin, alanine aminotransferase, lipase, troponin and creatinine and lower levels of lymphocytes, hemoglobin and sodium, while fibrinogen was inconsistently elevated." (PMID 37231476, 2023). "The elevated levels of IL-6, D-dimers, CRP, neutrophils, and a low lymphocyte count have been associated with severe forms of COVID-19." (PMID 38203482, 2023). "Strands of research support the study of systemic inflammatory pathways in obesity-associated severe COVID-19 since significantly higher CRP, ferritin, and ESR values have been found." (PMID 36851702, 2023). "Among COVID-19 patients, higher C-reactive protein levels were associated with higher mortality risk with a saturation effect." (PMID 37990060, 2023). "We used a Cox proportional hazards regression model to adjust for age, ethnicity, steroid use, baseline C-reactive protein, and COVID-19 variant." (PMID 37598275, 2023). "Specific biomarkers associated with severe COVID-19 illness in cancer patients include C-reactive protein (CRP) and interleukin (IL)-6." (PMID 36673615, 2023). "Male sex, increasing age, hypoxemia, hypoglycemia or hospital hyperglycemia, AST–ALT ratio >1, elevated CRP, altered arterial pH, and leucocytosis were factors significantly associated with higher mortality in patients hospitalized with COVID-19." (PMID 37459312, 2023). "It has previously been shown that CRP increased in COVID-19 patients and this increase is associated with the severity of the disease." (PMID 36788868, 2023). "The proposed architecture makes use of CXR pictures and only five parameters: LDH, O2%, Age, WBC, and CRP, and demonstrates exceptional results for recognizing low- and high-risk COVID-19-positive individuals with extremely high sensitivity." (PMID 37362565, 2023). "Meanwhile, CRP stands out as one of the highly efficient biomarkers for predicting mortality risk associated with COVID-19." (PMID 37628401, 2023). "Eleven parameters were analyzed as potential risk factors: age, days since COVID-19 onset, days since pulmonary embolism diagnosis, obesity, D-dimer, CRP, WBC, platelets, PaO2/FiO2, ferritin, and presence of right heart thrombus." (PMID 37515199, 2023). "Elevated serum CRP levels are key markers of disease progression and a risk factor for mortality in severe COVID-19 patients and have been reported to be indicative of a developing cytokine storm in COVID-19 patients." (PMID 36919085, 2023). "In this regard, CRP levels greater than 10 mg/dL were reported to be significantly associated with higher odds of COVID-19-related mortality (13.56, p = 0.03) in patients with leukemia, myeloma and lymphoma." (PMID 36673615, 2023).
COVID-19 (continued). "IL-6 is a powerful pro-inflammatory cytokine that stimulates the C-reactive protein (CRP) and is identified as a driver of the COVID-19 cytokine storm associated with a poor outcome." (PMID 36851766, 2023). "For levels greater than or equal to 40 mg/L, CRP has been suggested as a reliable indicator of COVID-19 severity and risk of death." (PMID 38256320, 2023). "A decrease in lymphocyte levels has been previously linked to a higher mortality risk, and an increase in CRP is linked to a severe prognosis in COVID-19 patients." (PMID 37623875, 2023). "We previously proposed sPD-L1 as a valuable prognosis biomarker for COVID-19, having found that high levels of sPD-L1 correlated with low lymphocyte counts and high CRP levels and were also associated with longer hospital length of stay (LOS) and death." (PMID 37959277, 2023). "Neutrophilia, lymphopenia, and high CRP levels are closely linked with the pathophysiology of COVID-19." (PMID 37373750, 2023). "Elevated CRP levels in the early stages of COVID-19 have been associated with lung destruction and disease severity." (PMID 37241099, 2023). "In this study, we demonstrated a causal relationship between CRP, an inflammatory marker, and COVID-19-related prothrombotic state." (PMID 36619223, 2023). "CRP levels are used for risk stratification for COVID-19, Dengue Virus (DENV), and Human Immuno-deficiency Virus (HIV) infections." (PMID 39554800, 2023). "Other studies have shown a positive association between elevated CRP levels and disease severity and mortality in COVID-19." (PMID 37744227, 2023). "In conclusion, the inflammatory response in hospitalized COVID-19 patients, determined by biomarkers such as CRP, ferritin, PCT or LDH, is similar between infections caused by different VOCs between 2021 and 2022." (PMID 37908351, 2023). "Male sex, increasing age, hypoxemia, hypoglycemia or hospital hyperglycemia, AST–ALT ratio >1, elevated CRP, altered arterial pH, and leucocytosis were factors significantly associated with higher mortality in hospitalized patients with COVID-19." (PMID 37459312, 2023). "Possessing higher DII and E-DII values, being of the male gender, having higher education, and being a smoker were associated with higher CRP in patients with COVID-19." (PMID 37063325, 2023). "Nevertheless, the impact of C-reactive protein (CRP) on the progression of COVID-19-associated pneumonia remains to be elucidated." (PMID 38077346, 2023). "Recently, some studies also found ACEI/ARB can significantly reduce COVID-19 caused pulmonary inflammation by inhibiting the levels of IL-6, C-reactive protein and calcitonin." (PMID 36634085, 2023). "We found that COVID-19 severity was directly linked to age, scoring index of chest x-ray, percentage of neutrophils, albumin, CRP, and ratio of lymphocytes." (PMID 36668902, 2023). "As compared with log KL-6 and log D-dimer, log CRP showed the strongest association with progression to severe COVID-19 (HR 2.079, 95% CI 1.389–3.113; p < 0.001)." (PMID 36979833, 2023). "Interleukin-6 (IL-6) and oxygenation index (PaO2/FiO2) were missing in over 97% of hospitalizations and C-reactive protein and ferritin over 98% of the time; despite all four being identified as risk factors for COVID-19 related mortality." (PMID 36800930, 2023). "Elevated serum levels of CRP are associated with thrombotic disease and mortality in COVID-19 patients." (PMID 36979908, 2023). "In patients with venous thromboembolism in association with COVID-19, laboratory tests indicate high levels of prothrombotic markers (fibrinogen and D-Dimer), and inflammatory markers (C reactive protein, IL-6), which are related to hypercoagulable state." (PMID 36851619, 2023). "In fact, both groups showed increased levels of biochemical parameters that have been associated with a higher risk of a poor outcome of COVID-19, such as C-reactive protein (CRP) and lactate dehydrogenase (LDH)." (PMID 36767310, 2023).
COVID-19 (continued). "Many exposures increase the susceptibility and severity of COVID-19, such as cardiovascular and metabolic disorders, high BMI, C-reactive protein (CRP), and smoking." (PMID 37867515, 2023). "The proteolytically cleaved form of the Gal-9 protein showed potential to become an additional (to D-dimer and CRP) diagnostic marker but specific to assessing COVID-19 severity." (PMID 40729168, 2023). "Higher CRP level, requiring increased use of steroids and Tocilizumab were associated with aggravated COVID-19 cases." (PMID 37643201, 2023). "The plasma CRP level was positively correlated with COVID-19 severity, and a higher CRP level was associated with a longer inpatient duration." (PMID 36668902, 2023). "Our study aimed to evaluate the association of PCT and CRP with secondary infections acquired during ICU stay in critically ill COVID-19 patients." (PMID 37887237, 2023). "Thrombocytosis increased the risk of ischemia, which was expected, and high D-dimer, fibrinogen and CRP levels increased the risk of stroke in patients with concurrent COVID-19 and acute ischemic CVD." (PMID 36016071, 2022). "The greatest risk of death from COVID-19 was age above 75 years, worsened by elevated CRP and CXR score and reduced P/F." (PMID 33683539, 2022). "Multiple candidate clinical parameters, including LYMPH and CRP involved in this study, have been shown to be closely associated with disease severity, rapid progression, and clinical prognosis in COVID-19 patients." (PMID 36248811, 2022). "This can be explained by the fact that CRP is associated with a larger number of comorbidities and patients were only recruited if they had clinical suspicion of COVID-19." (PMID 36137157, 2022). "It is known that hyper inflammation can occur during the clinical course of the disease and that elevated plasmatic level of inflammatory biomarkers (such as CRP) were associated with COVID-19 severity." (PMID 34995292, 2022). "Radiologic and laboratory findings showed a higher use of megadose therapy among patients with an interstitial infiltrate and elevated inflammatory markers associated with COVID-19, such as elevated lactate dehydrogenase and C-reactive protein, on admission." (PMID 35061713, 2022). "A quarter of the patients with progression to COVID-19-associated ARDS presented with macrophage activation syndrome: high levels of CRP, ferritin, d-dimer, AST/ALT, tumor necrosis factor (TNF)-alpha, interleukin (IL)-1beta and IL-6." (PMID 36289881, 2022). "We found that the NEWS score was a better indicator of COVID-19 severity in DM+ and DM– patients, and that it was also associated with CRP, D-dimer, total leukocyte, and neutrophil levels." (PMID 35766706, 2022). "We aimed to describe body composition changes up to 6–7 months after severe COVID-19 and to evaluate their association with COVID-19 inflammatory burden, described by the integral of the C-reactive protein (CRP) curve." (PMID 36145141, 2022). "High-dose interleukin-1 blockade can cause a decrease in serum C-reactive protein and improve respiratory function in COVID-19 patients around 21 days." (PMID 35747501, 2022). "Marked elevations in hematologic biomarkers, such as LDH, D-dimer, ferritin and CRP, are associated with worse outcomes in COVID-19." (PMID 36556258, 2022). "Out of 32 studies, 20 showed a nearly four-fold higher risk of poor outcomes in COVID-19 patients with elevated CRP." (PMID 36560453, 2022). "Infection with COVID-19 causes a “cytokine storm” with increased CRP and IL-6, and these predict disease severity and poorer outcomes." (PMID 36614901, 2022). "Studies suggest that COVID-19-associated coagulopathy and inflammatory parameters such as CRP levels are survival determinants." (PMID 36289811, 2022). "The proinflammatory biomarkers related to the Th-1 pathway such as leukocytes, neutrophils, CRP, and D-dimer were significantly associated with mortality in patients with severe COVID-19." (PMID 36465942, 2022).
COVID-19 (continued). "The symptoms of virus infection alone or bacterial co-infection are not always clear, so laboratory inflammatory markers associated with bacterial infection, such as high C-reactive protein, are significant in COVID-19 patients with bacterial co-infections." (PMID 36365001, 2022). "In COVID-19, several studies found that an increased CRP was associated with disease severity and poor progression." (PMID 35683357, 2022). "Other important factors independently associated with COVID-19 mortality in the literature included advanced age, increased C-reactive protein, reduced renal function, coronary artery disease, increased frailty, and poor preadmission functional status." (PMID 35629983, 2022). "We found older age, dyspnea/shortness of breath, and laboratory characteristics such as high CRP and lymphocytopenia (low lymphocyte) at admission were associated with oxygen requirement among COVID-19-infected patients." (PMID 35683357, 2022). "High serum CRP levels are key markers of disease progression and a risk factor for mortality in patients with severe COVID-19, and indicate the development of a cytokine storm." (PMID 35807783, 2022). "In summary, significant elevations of the inflammatory marker CRP are independently associated with prolongation of the QTc interval in hospitalized COVID-19 patients." (PMID 35811700, 2022). "The fact that our case was in the period of COVID-19 pandemic, had a history of domestic contact for COVID-19, and fever, cough, weakness, abdominal pain, and high CRP caused COVID-19 to be considered in the differential diagnosis." (PMID 36258988, 2022). "Outcomes of interest included all-cause mortality, COVID-19 severity, mechanical ventilation, C-reactive protein and D-dimer levels." (PMID 35381033, 2022). "Our study suggests incorporating these CRP, IL-6 and D-dimer markers to design discriminatory tools and risk stratification tools to adequately identify COVID-19 patients with poor clinical outcomes." (PMID 35261542, 2022). "A previous report showed that the severity and mortality of COVID-19 are associated with elevated levels of serum CRP, ferritin, and D-dimer." (PMID 36226145, 2022). "The purpose of the study was to study the effect of the acute phase of COVID-19 on thyroid function, assess the influence of the severity of the disease on thyroid function, and the association of these derangements with CRP." (PMID 35706733, 2022). "LDH, D-dimer, fibrinogen, CRP, and low platelets, markers of thrombotic risk, have been reported to be associated with poor prognosis in COVID-19." (PMID 35864532, 2022). "In adult studies, raised levels of CRP are associated with severity and mortality in COVID-19 patients." (PMID 36225458, 2022). "Age, elevated CRP, and tachycardia were independent risk factors for mortality in COVID-19 patients admitted to the ICU." (PMID 35154932, 2022). "The only ones associated with severe COVID-19 included CRP (adjusted odds ratio (aOR) 1.04, 95% confidence interval (CI) 1.02–1.06; p < 0.01) and sFlt-1/PlGF ratio (aOR 1.04, 95% CI 1.02–1.05; p < 0.01)." (PMID 36429772, 2022). "Hypoalbuminemia, elevated CRP, and elevated d-dimer and Ferritin are associated with adverse outcome among COVID-19 as previously shown in other studies." (PMID 36962449, 2022). "In line with our findings, CRP stood out as the single factor associated with severe COVID-19 in multivariable analysis in a nested case-control study of 134 COVID-19 patients." (PMID 35407418, 2022). "LDH, CRP, and D-dimer have been identified by the majority of machine learning models as important risk laboratory parameters linked to COVID-19 disease severity." (PMID 35746672, 2022). "The laboratory findings of a higher neutrophil count, D-dimer, ferritin, c-reactive protein (CRP), and low lymphocyte count have been reported in severe COVID-19 and were associated with unfavorable prognosis." (PMID 35053224, 2022).